MAEL (maelstrom spermatogenic transposon silencer)
Diseases named in the same sentence as MAEL in open-access papers (continued):
Sharing a sentence is not in itself a finding about the gene and the disease.
tumor (13 papers, 2014 to 2024). "Taken together, MAEL expression was associated with inactivated anti-tumor immunity, activated pathways concerning VEGFR and PI3K-AKT-mTOR, and sensitivities to VEGFR/PI3K-AKT-mTOR inhibitors in ccRCCs." (PMID 38301040, 2024). "High MAEL expression was associated with an anti-inflammatory tumor immune microenvironment and VEGFR/mTOR activation in ccRCC tissues and high sensitivities to VEGFR/PI3K-AKT-mTOR inhibitors in ccRCC cell lines." (PMID 38301040, 2024). "MAEL protein expression in the cytoplasm of partial tumor cells was observed in two ccRCC samples of the HPA database using immunohistochemical staining." (PMID 38301040, 2024). "The suppression effect of MAEL knockout in tumor aggressiveness was rescued in PTGS2 overexpression HCC cells." (PMID 35740546, 2022). "Although, there was not any significant correlation between tumor size and levels of MAEL mRNA expression in general population, there was a significant correlation between MAEL expression and tumor size among male patients (p = 0.028)." (PMID 33902648, 2021). "MAEL can be involved in ESCC progression by regulation of AKT1/RelA/IL8 signaling to recruit Myeloid-Derived Suppressor Cells (MDSCs) to tumor sites." (PMID 33902648, 2021). "In present study, we assessed the levels of MAEL mRNA expression in Iranian ESCC patients to determine its probable role during tumor progression and metastasis." (PMID 33902648, 2021). "Transfection-induced overexpression of LINC00511 and MAEL, as well as downregulation, highlighted the features of tumor cells, and LINC00511 overexpression reduced apoptosis in vitro." (PMID 31386627, 2019). "The expression level of MAEL was negatively mediated by miR-618 in OS cells, and downregulation of MAEL plays a tumor-inhibiting role in OS cells." (PMID 31386627, 2019). "Recently several other studies investigated the effect of PIWI and MAEL overexpression on tumor progression." (PMID 24932571, 2014). "Our work shows that PIWIL1 and MAEL expression is significantly increased in malignant EOC (n = 25) compared to benign tumor tissues (n = 19) and normal ovarian tissue (n = 8)." (PMID 24932571, 2014). "MAEL promotes tumor growth by inhibiting the apoptosis of cells." (PMID 35488386, 2022). "A number of the identified tumour-associated antigens are known to signal via this cascade, HMGN5, TFG, MAEL, SOX15 and Dicckopf-1, the latter of which has been investigated in numerous other biomarker signatures and like TFG interacts via the Wnt co-receptor LRP6." (PMID 34728792, 2022). "Previous studies have identified MAEL as an oncogene promoting tumor aggressiveness in liver and provided clues indicating that MAEL could enhance self-renewal and chemoresistance capabilities through regulatory stemness-related genes." (PMID 35740546, 2022). "The deletion of MAEL led to a marked reduction in the tumor masses in mice." (PMID 35740546, 2022). "Our results showed higher MAEL expression with increasing tumor stage." (PMID 33374923, 2020). "Furthermore, PIWIL2 and MAEL are co-expressed in the stromal cells adjacent to tumor cells." (PMID 24932571, 2014). "In summary, these results demonstrated that MAEL is involved in EOC cell invasion and EOC metastasis, and has strong tumor-promoting effects in EOC." (PMID 35513870, 2022). "MAEL is overexpressed in EOC, and the upregulation of MAEL promotes tumor cell migration, invasion, and metastasis by inducing EMT." (PMID 35513870, 2022). "Using IHC, we demonstrated that the overexpression of MAEL in EOC was closely related to pT/pN/pM status, tumor histological grade, and advanced FIGO stage, and also acted as a predictor of poor patient survival." (PMID 35513870, 2022). "REXO2, MSI1, and ESRP2 had high expression levels in tumors compared with normal tissues, while CTU1, MAEL, and YBX2 were undetermined in both tumor and normal tissues." (PMID 33193734, 2020).
tumor (continued). "In situ hybridization on tumor sections revealed that L1, PIWIL1, 2 and MAEL are specifically expressed in epithelial cells (cancerous cells) of EOC." (PMID 24932571, 2014). "Furthermore, the high expression of MAEL has been correlated closely with epithelial-mesenchymal transition (EMT), tumor aggressiveness and poor patient prognosis." (PMID 35513870, 2022). "The overexpression of MAEL in MIHA and Huh7 cells resulted in larger tumor masses in nude mice." (PMID 35740546, 2022). "Taken together, these results propose that MAEL may promote EOC cell invasion and tumor metastasis via regulation of FGFR4." (PMID 35513870, 2022). "Our observation of MAEL overexpression in the absence of detectable L1 expression in early stage tumor samples raises the possibility that non-functional MAEL may play a role in decreasing DNA methylation promoting subsequent L1 expression." (PMID 24932571, 2014).
benign tumors (2 papers, 2014 to 2020). "RNA methyltransferase HENMT1 and spindle class gene MAEL both had significantly increased expression in HGSOC tumors compared to benign tumors." (PMID 33374923, 2020). "The expression of PIWIL1 and MAEL however is significantly increased in malignant EOC when compared to benign tumors." (PMID 24932571, 2014). "In this study, we investigated the expression of PIWIL1–4 and MAEL in 25 EOC, 19 benign tumor samples, and 8 normal ovarian tissues." (PMID 24932571, 2014).
adenocarcinoma (1 paper, 2017). A common cancer characterized by the presence of malignant glandular cells. "To investigate whether MAEL expression was regulated by gene amplification or DNA methylation, we analyzed the correlation between DNA variation and mRNA expression using cBioPortal based on the Stomach Adenocarcinoma data (TCGA, Provisional)." (PMID 29371914, 2017).
nervous system tumors (1 paper, 2024). "Similarly, in the CCLE database (abbreviations), high MAEL expression was observed in nervous system tumors and KIRC." (PMID 38301040, 2024).
MAEL also shares sentences with these, for which no sentence is quoted: clear cell renal cell carcinoma (1 paper); connective tissue disorder (1); esophageal squamous cell carcinoma (1); invasive breast carcinoma (1); liver cancer (1); papillary renal cell carcinoma (1); testicular germ cell tumor (1).